ETV5 (ETS variant transcription factor 5)
Description:
Binds to DNA sequences containing the consensus nucleotide core sequence 5'-GGAA.-3'.
Synonyms: ERM
Tractability: Antibody: its Gene Ontology location is reachable by antibodies, with medium confidence. PROTAC: UniProt records ubiquitination sites on it; ubiquitination databases record sites on it.
Gene: Protein-coding gene on chromosome 3 (186,046,314 to 186,110,318, reverse strand). Ensembl gene ENSG00000244405.
Subcellular location: Nucleus
Subcellular location (Human Protein Atlas): Nucleoplasm
Gene Ontology:
Molecular function: DNA-binding transcription activator activity, RNA polymerase II-specific; DNA-binding transcription factor activity; protein binding; RNA polymerase II transcription regulatory region sequence-specific DNA binding; sequence-specific double-stranded DNA binding; transcription cis-regulatory region binding; DNA binding; DNA-binding transcription factor activity, RNA polymerase II-specific; sequence-specific DNA binding
Biological process: cellular response to oxidative stress; negative regulation of transcription by RNA polymerase II; positive regulation of transcription by RNA polymerase II; cell differentiation; regulation of transcription by RNA polymerase II; regulation of DNA-templated transcription
Cellular component: nucleoplasm; nucleus; chromatin
Genetic constraint (gnomAD): Loss-of-function variants: 10 observed, 72.66 expected, observed/expected ratio (o/e) 0.14, 90% interval 0.084 to 0.23. The upper end of that interval is the gene's LOEUF score, 0.23, which puts it in group 1 of 6, group 1 being the genes least tolerant of losing a copy. Missense variants: 451 observed, 669.56 expected, observed/expected ratio (o/e) 0.67, 90% interval 0.62 to 0.73. Synonymous variants: 216 observed, 245.59 expected, observed/expected ratio (o/e) 0.88, 90% interval 0.79 to 0.99.
Homologues: Orthologues: macaque ETV5 (99% identical), chimpanzee ETV5 (99% identical), pig ETV5 (97% identical), rabbit ETV5 (96% identical), dog ETV5 (96% identical), guinea pig ETV5 (96% identical), mouse Etv5 (95% identical), rat Etv5 (95% identical). Paralogues in human: ETV1 (60% identical), ETV4 (50% identical), ETS1 (21% identical), ETS2 (20% identical), FLI1 (17% identical), GABPA (17% identical), ELF2 (16% identical), ERG (16% identical), ELF1 (15% identical), ETV6 (15% identical), ELF4 (14% identical), ETV2 (13% identical), and 16 more.
Diseases named in the same sentence as ETV5 in open-access papers:
ETV5 is named in the same sentence as 95 diseases in open-access papers, as found by Europe PMC text mining. Sharing a sentence is not in itself a finding about the gene and the disease. The quoted sentences say what the papers report.
Obesity (24 papers, 2010 to 2025). Accumulation of substantial excess body fat. "The ETV5 gene is involved in hepatic FA metabolism by binding to PPAR response elements, and the ETV5 transcription factor has been associated with obesity in genomic association studies." (PMID 40598589, 2025). "It has been demonstrated that a total loss of function of ETV5 results in reduced diet-induced obesity and severe glucose intolerance." (PMID 36872348, 2023). "Genome-wide association studies have revealed an association of ETV5 with human obesity in multiple populations." (PMID 36872348, 2023). "As a reaction to different nutrient states, expression of ETV5 changes in specific brain areas of adult rats, suggesting that ETV5 functions as an obesity-associated gene in the brain." (PMID 36872348, 2023). "In an epigenetic association study, researchers found that Etv5, Nudt3, Wwox, Zeb1, and Maf DNA methylation alterations were related to obesity in peripheral blood leukocytes of humans." (PMID 35458198, 2022). "This is due to increased Cul4 neddylation, CRL4COP1 E3 assembly, and ubiquitylation of ETV5, an obesity-associated transcriptional suppressor of insulin secretion." (PMID 33911083, 2021). "According to literature, the ETV5 gene has been associated with BMI in multiple GWAS studies and functionally linked to obesity." (PMID 31527397, 2019). "Here we demonstrate, using whole transcriptome analysis, that Drosophila Ets96B, homologue of obesity-linked gene ETV5, regulates cellular systems associated with obesity and BD." (PMID 27280443, 2016). "Two GWAS in populations of European ancestry identified SNPs near ETV5 as associated with BMI and obesity." (PMID 25825681, 2015). "The transcription factor ETS version 5 (Etv5) is one of these obesity-associated genes, implicating Etv5 in the etiology of obesity." (PMID 24710089, 2014). "ETV5 is linked to body mass index and other obesity-related traits in GWAS10–12." (PMID 33911083, 2021). "Finally, the new association of ETV5 to human bipolar disorder emphasizes a functional relationship between obesity and BD at the molecular, as well as behavioural level." (PMID 27280443, 2016). "In humans the obesity-linked gene ETV5 was also associated with bipolar disorder." (PMID 27280443, 2016). "Finally, a connection between the obesity-linked gene ETV5 and bipolar disorder emphasizes a functional relationship between obesity and BD at the molecular level." (PMID 27280443, 2016). "Research has demonstrated that Etv5 is an obesity-related transcriptional inhibitor of insulin secretion and is closely associated with obesity and type 2 diabetes." (PMID 39840059, 2024). "ETV5 is an obesity-related gene which plays important roles in the regulation of energy balance and metabolism." (PMID 36872348, 2023). "The CRL neddylation inhibitor Pevonedistat/MLN4924 stabilizes ETV5 and remediates the hyperinsulinemia and obesity/diabetes phenotypes of these mice." (PMID 33911083, 2021). "MLN4924 also attenuates excessive ETV5 degradation, obesity, and diabetes development in ob/ob mice, improving their hyperglycemia, hyperinsulinemia, glucose tolerance, and insulin sensitivity." (PMID 33911083, 2021). "The clinical relevance of ETV5 as a CRL4COP1-degradable checkpoint in feeding-induced insulin secretion is underscored by GWAS identification of ETV5 as a diabetes/obesity-related gene." (PMID 33911083, 2021). "A recent study showed that upon glucose stimulation or HFD-feeding, CRL4COP1 E3 ligase can promote ETV5 degradation in pancreatic islet cells, thus mediating insulin over-secretion and promote insulin resistance and obesity." (PMID 34716308, 2021). "Studies also have indicated the relationship between diet and obesity and ETV5 gene expression, which participates in food intake control mechanisms." (PMID 32831068, 2020). "Etv5 knockout mice exhibit lean bodies, resistance to diet-induced obesity and severe glucose intolerance due to impaired insulin exocytosis and hypoinsulinaemia." (PMID 25825681, 2015).
Obesity (continued). "Both the ETV5 rs7647305 C-allele and the GNPDA2 rs10938397 A-allele associated with increased risk of obesity with ORs 1.18 (1.08–1.29, p = 1.8×10−4) (rs7647305) and 1.15 (1.07–1.23, p = 1.1×10−4)) (rs10938397), but not with overweight or morbid obesity." (PMID 21912638, 2011). "By further analysing these adult obesity susceptibility loci in the ALSPAC birth cohort, with the addition of variants in BDNF and ETV5, we aimed to identify the specific timing of childhood weight gain and growth associated with adult obesity risk." (PMID 20520848, 2010). "The obesity-risk-allele score based on genotypes at eight SNPs associated with childhood BMI (in/near to: FTO, MC4R, TMEM18, GNPDA2, NEGR, KCTD15, BDNF, and ETV5) ranged from 2 to 15 alleles." (PMID 20520848, 2010). "Additionally, Etv5 is considered a transcriptional suppressor of insulin secretion related to obesity and a novel transcription factor involved in regulating hepatic fatty acid metabolism." (PMID 39840059, 2024). "In ConvR HFD mice liver, 17 genes DNA methylation changes including Ube2l3, Etv5, Lrp1, and Nudt3 were determined related to obesity and 11 genes DNA methylation changes including Exoc312, Mst1r, Prkch, and Arhgap26 were determined related to Type 2 diabetes (T2D) in the previous study." (PMID 35458198, 2022). "Indeed, MLN4924 attenuates HFD-induced ETV5 degradation, obesity, hyperinsulinemia, hyperglycemia, glucose intolerance, and insulin resistance." (PMID 33911083, 2021). "Our work delineates the changes in chromatin accessibility in monocytes and ATMs during obesity, and identifies ETV5 as a critical transcription factor suppressing ATM activation, suggesting its potential use as a therapeutic target in obesity-related chronic inflammation." (PMID 34716308, 2021). "Additionally, we reveal that multiple SNPs in human ETV5 link to body mass index (BMI) and BD, providing further evidence for ETV5 as an important and novel molecular intermediate between obesity and BD." (PMID 27280443, 2016). "Thus, targeting ETV5 in macrophages may be a suitable strategy for the treatment of obesity and other chronic inflammatory diseases." (PMID 34716308, 2021). "Thus, ETV5 may play different roles in ATMs and adipocytes during the development of obesity." (PMID 34716308, 2021). "Therefore, we aimed to determine whether ETV5 can regulate macrophage activation in obesity." (PMID 34716308, 2021). "Genotype distributions were not related to drop-out rates except for ETV5 and FAIM2, which had more completers among homozygotes than among non-carriers of the obesity risk-allele (P = 0.01 and 0.02 respectively), and for PTBP2, which showed the opposite pattern (P = 0.03)." (PMID 22952648, 2012). "Finally, RNA-seq results showed that the transcription factor ETV5 is associated with the IL-6 production pathway and inflammatory response in macrophages, indicating that the function of ETV5 in regulating inflammation may not be limited to ATMs in obesity." (PMID 34716308, 2021).
prostate carcinoma (24 papers, 2008 to 2023). A carcinoma that arises from epithelial cells of the prostate gland. "PEA3 transcription factors Etv1, Etv4, and Etv5 overexpression is associated with the development and metastasis of prostate cancer, colorectal cancer, and ovarian cancer." (PMID 30610188, 2019). "Also, it is obtained that most of the studied genes (TMPRSS2, ERG, ETV5 and AR) are associated with pathways involved in the development of prostate cancer." (PMID 37287057, 2023). "In prostate cancer, ETV5 promoted the EMT and cell migration through transcriptional regulation of TAFAZZIN expression." (PMID 36872348, 2023). "It shares an implication in prostate cancer with ETV5, AR and ERG; while ACE2 shares its importance in the development of COVID-19." (PMID 37287057, 2023). "ETV5 was shown to induce a more aggressive and infiltrative pattern of prostate cancer cells in the former study." (PMID 31937834, 2020). "We identified ETV5, a bona fide oncogene in prostate cancer, as robustly upregulated in neuroblastoma cells harbouring ALK mutations, and show high ETV5 levels downstream of the RAS/MAPK axis." (PMID 31937834, 2020). "ETS transcription factors have a role in oncogenesis and ETV5 gene fusions have been described in prostate cancers." (PMID 31027231, 2019). "Whilst this manuscript was under review, it has been reported that indeed ETV1, ETV4 and ETV5 can transcriptionally upregulate TAZ in prostate cancer cells." (PMID 30952872, 2019). "Lastly, ETV4 and ETV5 are highly homologous to ETV1 and also implicated in prostate cancer development." (PMID 31160676, 2019). "Recurrent gene fusions involving several members of ETS transcription factor family (ERG, ETV1, ETV4 or ETV5) were found to be the most frequent genetic alterations in prostate cancer, which can be detected in as many as 50%–70% of prostate cancer samples." (PMID 23852643, 2013). "Especially TMPRSS2 fuses with ERG and Ets family genes such as ETV1, ETV4 and ETV5 in prostate cancers." (PMID 21347291, 2011). "It is possible that like the fusions between TMPRSS2 and ERG, ETV1, ETV4 and ETV5, other functionally identical fusions are involved in changes in gene expression and prostate cancer development but are yet to be discovered." (PMID 18694509, 2008). "Notably, AR and multiple transcription factors extensively reported to be involved in prostate cancer aggressiveness, such as ETV5 and ETV1 were identified as Key TFs with increased transcriptional targets, supporting the biological relevance of our analysis." (PMID 30314329, 2018). "In prostate cancer samples, SLC45A3 was also found to be a 5′ fusion partner, and exon 8 of ETV5 was fused to exon 1 of SLC45A3, resulting in ETV5 gene rearrangements." (PMID 36872348, 2023). "Researchers discovered rare 5′ fusions of ETV5 with TMPRSS2 and solute carrier family 45 member 3 (SLC45A3) in prostate cancer." (PMID 36872348, 2023). "The discovery and functional validation of recurrent gene fusions of 5 Ets factor genes (ETV1, ETV4, ETV5, ERG, Fli1) in prostate cancer highlights the relevance of Ets transcription factors as oncogenes in prostate cancer." (PMID 26885618, 2016). "ETS family gene fusions, primarily including ERG (and less frequently, ETV1, ETV4, ETV5 or FLI1), are found in approximately 50 % of prostate cancers, the most common fusion being TMPRSS2-ERG." (PMID 26684754, 2015). "Conversely, some lineage-specific genes are seen to serve as 5′ partners across multiple different 3′ genes; for example, TMPRSS2 and SLC45A3 in prostate cancer have been observed as 5′ partners of ERG, ETV1, ETV4, ETV5, BRAF, and ELK4." (PMID 26684754, 2015). "The most prevalent gene fusion is the TMPRSS2-ERG, present in nearly half of all human prostate cancers, followed by rearrangements involving the ETV1, ETV4, ETV5 and FLI1 genes, often with promoter fusion partners other than TMPRSS2." (PMID 25595908, 2015).
prostate carcinoma (continued). "TMPRSS2 is also strongly related with other genes involved in prostate cancer, like ERG, ETV5 and AR, whose characterization could help to clearly classifying COVID-19." (PMID 37287057, 2023). "ETV1, ETV4, and ETV5, which belong to the PEA3 group of genes, are types of ETS transcription factors that are known to promote several types of cancer such as Ewing-like sarcoma, gastric cancer, colorectal cancer, hepatocellular carcinoma and prostate cancer." (PMID 34830169, 2021). "Additionally, TMPRSS2-ERG fusions exist in approximately 50% of prostate cancer cases, with TMPRSS2-FEV, -ETV1, -ETV4, and -ETV5 fusions found in other patients." (PMID 34145397, 2021). "Anyway, the association between ETV5 or SOX9 expression level and the presence of AR variants in prostate cancer cells is not clear." (PMID 29069764, 2017). "Using the TaqMan Low Density Array (TLDA) technology, we evaluated the expression of the five ETS genes known to be involved in genomic rearrangements in PCa (ERG, ETV1, ETV4, ETV5 and FLI1) in a panel of cell lines representing various subtypes of prostate cancer." (PMID 25595908, 2015). "The protein dosage of PEA3 subfamily of ETS transcription factors ETV1, ETV4, and ETV5 is regulated through both transcription and ubiquitylation-mediated protein degradation by E3 ubiquitin ligase COP1, a tumor suppressor in both human prostate cancer and in GEM models of prostate cancer." (PMID 37018402, 2023). "Interestingly, the prostate carcinoma cell lines PC3 and MDA-PCa-2b exhibited a remarkable co-expression of the three members of the PEA3 subfamily of ETS transcription factors (ETV1, ETV4 and ETV5)." (PMID 25595908, 2015).
colorectal cancer (14 papers, 2019 to 2024). A primary or metastatic malignant neoplasm that affects the colon or rectum. "E26 transformation-specific variant transcription factor 5 (ETV5) contributes to tumor growth and progression and promotes colorectal cancer (CRC) angiogenesis." (PMID 33931578, 2021). "Recently, a study found that colorectal cancer patients with positive expression of ETV5, a member of the ETS transcription factor family that can trigger angiogenesis by upregulating VEGFA, are resistant to bevacizumab." (PMID 36077785, 2022). "ETV5 identified in colon carcinoma cell lines has been reported to be abnormally upregulated in the colorectal cancer and positively correlated with the tumor size, lymphatic metastasis, tumor node metastasis, and worse survival." (PMID 36528241, 2022). "In our previous study, ETV5 mediated-angiogenesis was demonstrated to be dependent upon the PDGF-BB/PDGFR-β/Src/STAT3/VEGFA pathway in colorectal cancer (CRC)." (PMID 33099574, 2020). "Moreover, ETV5’s oncogenic role in colorectal cancer involves enhancing tumor proliferation and affecting the G1/S transition in the cell cycle, primarily by regulating p21 expression." (PMID 38515748, 2024). "In colorectal cancer model, the silencing of ETV5 suppresses cell proliferation." (PMID 37876309, 2023). "Indeed, the combination of anti-CCL2 and bevacizumab inhibited ETV5-positive colorectal cancer angiogenesis more efficiently than either of them alone." (PMID 36077785, 2022). "We observed that ETV5 corelates with cell proliferation markers in adjCTX treated patients in most of the datasets suggesting a significant role of ETV5 in cancer cell proliferation as observed in the colorectal cancer cells and other cancer cells." (PMID 33658938, 2020). "Moreover, it has previously been published that ETV5 contributes to tumor growth and progression in colorectal cancer, by binding directly to p21Cdkn1a promoter repressing its expression and upon ETV5 knockdown cell growth slows down, due to the inhibition of the repression of p21Cdkn1a." (PMID 37876309, 2023). "ETV5 may promote malignant progression of thyroid cancer through the PIK3CA signaling pathway, and ETV5 expression has also been associated with resistance to treatment with bevacizumab in colorectal cancer." (PMID 34335239, 2021). "During bevacizumab treatment of colorectal cancer patients with positive expression of ETV5, the secretion of CCL2 induced by ETV5 resulted in persistent angiogenesis, indicating that CCL2 plays a critical role in bevacizumab resistance." (PMID 36077785, 2022).